MTOR (mechanistic target of rapamycin kinase)
Diseases named in the same sentence as MTOR in open-access papers (continued):
Sharing a sentence is not in itself a finding about the gene and the disease.
cancer (continued). "mTOR pathway activation has been shown to induce improper DNA replication in various cancer cells, which contributes to drug resistance." (PMID 39668819, 2024). "Deregulated PI3K/Akt/mTOR signaling is a key driver of proliferation in many human cancers and has been shown to contribute to drug resistance in many types of neoplasia." (PMID 38539472, 2024). "RET is reported to participate in the development of malignant tumors by activating the AKT/mTOR signaling." (PMID 37874339, 2024). "This review analyzes the role of the mTOR pathway in quiescent cancer cells with the purpose of elucidating the biology of dormant cancer cells." (PMID 38418814, 2024). "Previous evidence indicates that upregulation of CENPM promotes cancer progression through the mTOR signaling pathway." (PMID 39325536, 2024). "We do not know the mechanism by which statins induce Akt1/Cav1 downregulation; nevertheless, statin-mediated attenuation of the Akt and mTOR signaling pathways has already been correlated with reduction of tumor burden in different cancers." (PMID 38473215, 2024). "The mTOR pathway is frequently dysregulated in cancer, making its inhibition a promising therapeutic strategy." (PMID 39766137, 2024). "mTOR can be activated by signal transduction pathways downstream of Ras, and chemical biology approaches have been used to target mTOR in cancers." (PMID 38931171, 2024). "Subsequently, with the discovery of the association between mTOR signaling and cancer, FDA-approved mTOR inhibitors have been employed in clinical trials for cancer treatment, while various other mTOR inhibiting molecules are currently under development." (PMID 39349424, 2024). "The KEGG analysis highlights the activation of the mTOR pathway following the initiation of cancer cell phagocytosis." (PMID 39766137, 2024). "Previous studies have extensively reported the involvement of UBE2C in cancer through the Akt/mTOR signalling pathway." (PMID 38690615, 2024). "It emphasizes the importance of understanding the specific miRNAs that target mTOR and their impact on radiosensitivity for personalized cancer treatment approaches." (PMID 38965615, 2024). "Similar to the effects of HT29 derived EV on AA uptake, AA synthesis and de novo protein synthesis, phosphorylation of mTOR and its downstream targets is most pronounced after stimulation with hypoxic cancer cell derived EV." (PMID 39001708, 2024). "STAT3 mediates the impacts of mTOR in macrophage-induced neoangiogenesis, potentially suggesting new insights into innate immune responses and new cancer therapy targets." (PMID 39003350, 2024). "Numerous studies show that YBX1 can promote drug resistance and cancer progression through the AKT/mTOR pathway." (PMID 38849679, 2024). "Identifying PIK3R1 mutations in 61.54% of patients further emphasizes the role of the PI3K/AKT/mTOR pathway in this cancer type, supporting the rationale for ongoing research into targeted therapies that inhibit this pathway." (PMID 39296440, 2024). "The senescent cells were observed to re-establish the tumor population after removing the mTOR inhibitors, indicating that suppressed mTOR activity is as a strong determinant of recurrent cancer cells despite the evidence of senescence." (PMID 38418814, 2024). "This implies the tumor-suppressive role of miR-1911-3p in modulating mTOR signaling by regulating mEAK7 in human cancers." (PMID 39770519, 2024). "Because the PI3K–Akt–mTOR pathway is the most frequently dysregulated pathway in human cancers, it has received intense scrutiny from the drug discovery community." (PMID 38992135, 2024). "While a few studies have described the crosstalk between O-GlcNAcylation and mTOR in the context of metabolic dysregulation, such as in cancer, their interaction under normal metabolic condition in β cells remains unexplored." (PMID 39388284, 2024). "KEGG analysis showed enriched pathways involved in mTOR and Hippo signalings, human cancers, and stem cell pluripotency." (PMID 38468074, 2024).
cancer (continued). "The development and progression of cancer have been linked to the dysregulation of multiple signaling pathways, including MAPK/ERK, Wnt/β-catenin, PI3K/AKT/mTOR, and NF-kB, which are among crucial pathways in cancer biology." (PMID 37863651, 2024). "In the AE group, KEGG pathway analysis revealed that the pathway of proteoglycans in cancer was the highest ranked, followed by the mammalian target of rapamycin (mTOR) signaling pathway, and axon guidance." (PMID 39845226, 2024). "Multiple studies have shown that cancers often exhibit excessive activation of the AKT/mTOR signaling pathway." (PMID 38773612, 2024). "The PI3K/mTOR inhibitor served a dual role—as a therapeutic agent and as a tool for rapid confirmation of successful drug delivery into cancer cells." (PMID 40115434, 2024). "At the molecular level, these alkaloids disrupt key signaling pathways in cancer cells, including mTOR, MAPK, EGFR, PI3K/AKT, and NF-κB." (PMID 39125943, 2024). "Targeting the PI3K/AKT/mTOR pathway has been proposed as an option for cancer prevention and intervention." (PMID 38833082, 2024). "The combination of BETi and mTOR inhibitors disrupted mTOR signaling and displayed superior anti-cancer activity than any single drug in vitro (JQ1/rapamycin) and in vivo (NHWD870/everolimus) assays." (PMID 38681203, 2024). "PU-H71 was found to disrupt the mTOR pathway, leading to decreased protein synthesis and enhanced apoptosis in cancer cells." (PMID 39564119, 2024). "LY3023414, the PI3K/mTOR/DNA‐PK inhibitor, pleotropic modulator CC‐122 and CC‐115, the mTOR/DNA‐PK inhibitor, not only target DNA‐PKcs, but also suppress cancer relevance kinases." (PMID 38898995, 2024). "According to some studies, an increase in Akap1 has been detected in cancer patients, with studies demonstrating that Akap1, which is a target of proto-oncogene, Myc, stimulates the mTOR pathway, resulting in the development of cancer." (PMID 38918814, 2024). "As a result, cancer cells with stem-like characteristics resume proliferation after the recovery of mTOR activity, explaining the phenotypical diversity of reversible drug-tolerant cells." (PMID 38418814, 2024). "PI3K/Akt/mTOR is a signaling pathway that plays a crucial role in tumorigenesis, cancer development, and cancer treatment." (PMID 39742381, 2024). "The mechanistic mTOR inhibition is well known to be a tool for generating quiescent stem cells and cancer cells." (PMID 38418814, 2024). "Despite the broad implications of mTOR inhibitors in cancer therapy, the link between aberrant alternative splicing, a process that can influence cancer progression by generating diverse protein isoforms, and mTOR activation in HCC remains unexplored." (PMID 39834948, 2024). "These ncRNAs activate the PI3K/Akt/mTOR pathway, promoting cancer cell proliferation, invasion, inhibiting apoptosis, and enhancing drug resistance." (PMID 39119480, 2024). "Recent reports substantiate the close relationship between BCAT1 expression and mTOR signaling activity in other cancers." (PMID 38309289, 2024). "Prior research has established that autophagy plays a crucial role as an indicator for the downstream of the pathway consisting of PI3K/AKT/mTOR in the process of drug‐induced death of cancer cells." (PMID 39436197, 2024). "In bladder cancer, intrinsic PD-L1 can also activate intrinsic cancer cell signals in a PD-1 independent manner and enhance cancer cell proliferation and survival by activating mTOR and inhibiting autophagy." (PMID 38762484, 2024). "UCA1 can act as a sponge for many tumor suppressor miRNAs, enhance cell cycle progression through different mechanisms, and interact with various cancer-related signaling pathways such as mTOR, AKT, Wnt, Hippo and JNK pathways." (PMID 39015175, 2024).
cancer (continued). "AMPK regulates the expression of PGC1-α, which controls mitochondrial biogenesis by activating p38 and inhibiting mTOR in cancer cells to regulate oxidative metabolism and maintain the ATP pool." (PMID 38745046, 2024). "The combination of mTOR inhibitors and chloroquine represents a promising area of research in cancer therapy." (PMID 39596342, 2024). "Several mTOR inhibitors have already been developed and many preclinical and clinical studies have corroborated the importance of mTOR inhibitors in cancer treatment." (PMID 38791040, 2024). "For example, mammalian target of rapamycin (mTOR) signaling can alter cancer cell metabolism, and metabolic shifts can subsequently sustain mTOR signaling and promote tumorigenicity." (PMID 39090094, 2024). "PTEN loss and EGFRvIII expression increase compound 60 sensitivity, which is consistent with increased efficacy in cancers with significant mTOR activation." (PMID 38686058, 2024). "Since cancers originate from CSCs, and mTOR signaling plays an important role in CSC regulation, the clinical potential and importance of mTOR in effective therapy are increasing." (PMID 39349424, 2024). "Decreased phosphorylation of mTOR and its downstream substrates reduces protein synthesis in cancer cells." (PMID 38729158, 2024). "The multifaceted actions of ridaforolimus within the mTOR pathway present promising avenues for cancer treatment and offer intriguing insights into its potential role in viral infections, adding a layer of versatility to its therapeutic applications." (PMID 38584599, 2024). "Compounds designed to inhibit specific metabolic pathways, such as glutaminase inhibitors and mTOR inhibitors, are showing promise in clinical settings, addressing the metabolic vulnerabilities of cancer cells." (PMID 39456607, 2024). "The PI3K/AKT/mTOR signaling axis meticulously orchestrates a multitude of cancer traits such as cell cycle progression, survival, differentiation, proliferation, migration, metabolism, and genetic stability." (PMID 39066845, 2024). "It is an anti-fungal agent that has been repurposed for cancer treatment due to its ability to reverse chemoresistance and to inhibit hedgehog and mTOR signalling, angiogenesis and autophagy." (PMID 39243069, 2024). "This dual mechanism targets both a lipid-signaling molecule, ceramide, and a key survival pathway, PI3K/AKT/mTOR, amplifying the potential anti-cancer effects of SsnB." (PMID 39770406, 2024). "Phosphorylation reactions stimulated by the PI3K/AKT/mTOR are responsible for cancer cell growth, proliferation, angiogenesis, tumour metastasis, and invasion." (PMID 38734930, 2024). "Numerous rapalogs and ATP-competitive mTOR inhibitors have been developed and many are currently in clinical trials as an immunosuppressant or as cancer therapeutic." (PMID 38940554, 2024). "Ridaforolimus, a promising mTOR inhibitor, has undergone extensive clinical evaluation, revealing a spectrum of AEs and demonstrating notable efficacy across various cancer types." (PMID 38584599, 2024). "Since mTOR has been known to modulate not only the cancer tissue itself but also those tumor immune systems, the role and importance of the mTOR in innate and adaptive immune responses is recently spotlighted." (PMID 39349424, 2024). "This is why several autophagy inducers targeting the PI3K/AKT/mTOR pathway have been synthesized or studied for their anti-cancer effects against different tumors, including GBM." (PMID 38672636, 2024). "PA containing OA has been previously shown in cancer cell lines to be a potent activator of mTOR signaling, In human trophoblast, mTOR activation up‐regulates System A activity." (PMID 38223199, 2024). "Overall, this review provides a comprehensive understanding of the potential of miRNAs targeting mTOR to enhance RT efficacy in cancer treatment and emphasizes the need for further research to translate these findings into improved clinical outcomes." (PMID 38965615, 2024).
cancer (continued). "The aberrant mTOR expression and activity in cancer cells can lead to uncontrolled cell growth and proliferation." (PMID 38474118, 2024). "Many mTOR inhibitors have been developed, but only a few of them have been approved to treat human cancer; the majority of mTOR inhibitors are currently undergoing evaluation in clinical trials." (PMID 38476632, 2024). "According to our transcriptome sequencing results, the PI3K/AKT/mTOR pathway is significantly affected, and previous studies have shown that the PI3K/AKT/mTOR pathway is correlated with cancer and glycolysis." (PMID 38916406, 2024). "FNBP1 was recently found to affect tumor survival, invasion, and metastasis through FAK/PI3K/AKT/mammalian target of rapamycin (mTOR) signaling, drawing connection between altered levels of cellular activity seen in both development and cancer." (PMID 39354505, 2024). "The mTOR signaling pathway plays an important inhibitory role in autophagy formation, and mTOR is considered a promising drug target for cancer therapeutic strategies." (PMID 38467935, 2024). "One mechanism is the activation of cell signaling pathways, such as the PI3K/AKT/mTOR pathway, which promotes cancer cell survival and proliferation and reduces the effectiveness of drugs." (PMID 39051060, 2024). "Metformin disrupts cancer cell metabolism via direct inhibition of mitochondrial respiration, the mammalian target of rapamycin (mTOR), and the phosphoinositide 3-kinase (PI3K)/protein kinase B (AKT) pathways in EC cells." (PMID 38570343, 2024). "mTOR, a serine/threonine kinase, is commonly activated in human cancers and plays a pivotal role in cancer development and treatment." (PMID 39469621, 2024). "Prior to deciding on the six genes, we looked at the functions of 582 proteins from LC-MS/MS analysis in cancer and found that, similarly to earlier research, the PI3K/AKT/mTOR pathway and cancer cell death were linked." (PMID 38361124, 2024). "In response to mTOR suppression, quiescent cancer cells dynamically change their proteome, triggering alternative non-canonical translation mechanisms." (PMID 38418814, 2024). "Everolimus is an mTOR inhibitor extensively used in the treatment of cancers, showing significant efficacy in improving progression‐free survival among patients." (PMID 39524139, 2024). "L-Leucine activates mTOR pathway, which has been suggested as a therapeutic target for BRCA1-deficient cancer." (PMID 38468344, 2024). "Especially interesting finding was that the DUSP6 knockdown cells displayed a gene expression pattern linked to dormant cancer cells such as inhibition of MYC, E2F1 targets, and the PI3K/AKT/mTOR signaling, as well as activation of the interferon response." (PMID 38886591, 2024). "By suppressing the PI3K/AKT/mTOR pathway, Parishin A reduces the signaling required for cancer cell proliferation and survival, leading to decreased tumor growth and potentially limiting metastasis." (PMID 39458918, 2024). "As one of the most mutated pathways among cancer cells, the PI3K/AKT/mTOR signaling pathway often results more resistant to ferroptosis in cells." (PMID 38583115, 2024). "Molecular alterations and elevated activity in the PI3K/AKT/mTOR signaling pathway are commonly observed in cancer." (PMID 39456780, 2024). "mTOR dysregulation is correlated with various systemic pathologies including cancer, arthritis, osteoporosis and IR." (PMID 39200267, 2024). "The mTOR and β-catenin signaling pathways are central to the regulation of cell growth, survival, and differentiation in various types of cancer, as well as UM." (PMID 38920653, 2024). "MTOR is a canonical regulator of S6K1 for protein synthesis and translation, and MTOR has been shown to be involved in EGFR-TKI resistance in various cancer types." (PMID 38397056, 2024).
cancer (continued). "They modulate the phosphorylation of key signaling proteins, such as Akt and mTOR, influencing the vital PI3K/Akt/mTOR signaling pathway in cancer cells." (PMID 38256183, 2024). "Previous researches have also demonstrated the involvement of DGKζ in regulating Akt/mTOR pathways in cancer cells, HEK293 cells, and C2C12 myoblasts 30-32." (PMID 38250603, 2024). "This recent study demonstrates that Torin 2 is the only mTOR inhibitor with the ability to suppress the self-renewal of cancer stem cells (CSCs) in GBM." (PMID 38474373, 2024). "Given the pivotal role of the PI3K/Akt/mTOR pathway in cancer development and progression, the antioxidant effects of carbazole derivatives offer a potential therapeutic strategy to combat cancer." (PMID 38773663, 2024). "The PI3K/AKT/mTOR pathway has been found to be dysregulated in most human cancers, especially breast cancer, and targeting this pathway has been proposed as a potential therapeutic option." (PMID 39437820, 2024). "Cancer cells under nutritional deficiency, hypoxia, and oxidative stress activates AMPK signaling, which leads to mTOR inhibition, thereby relieving the suppression of autophagy." (PMID 39201332, 2024). "The phosphorylation levels of key kinases in the PI3K/AKT/mTOR pathway are enhanced by lncRNA-H19 overexpression, which occurs in most cancer types." (PMID 38355574, 2024). "Different cell signaling pathways, such as PI3K, Akt, mTOR, MAPK/ERK, Wnt, Notch, and Hedgehog, are linked with the control of cancer cell proliferation, invasion, migration, angiogenesis, and metastasis." (PMID 39834817, 2024). "Recent characterization of molecular alterations in HNSCC has revealed that the PI3K/mTOR signaling pathway is the most frequently dysregulated pathway in this type of cancer." (PMID 39062182, 2024). "Further investigation by Jian Wang revealed that in PTEN-deficient cancer cells, a deficiency in PTEN is positively correlated with low STAT3 activity, likely due to hyperactivation of the PI3K/AKT/mTOR pathway." (PMID 39309860, 2024). "On the other hand, Wnt activation inhibits GSK3β by binding to the Axin-bound-GSK3β complex, promoting mTOR signaling and cancer cell proliferation." (PMID 39766864, 2024). "Specifically, the IGF family consisting of insulin, IGF-1, and IGF-2 regulates cellular functions relevant to cancer, including mediating the growth and survival of cancer cells (i.e., Akt and mechanistic target of rapamycin (mTOR) signaling)." (PMID 40443827, 2024). "The aberrant activation of the PI3K/AKT/mTOR pathway is a common occurrence in a multitude of cancers, and it serves to promote tumor growth and drug resistance." (PMID 39559367, 2024). "This is achieved by exerting inhibitory effects on the PI3K/Akt/mTOR signaling cascade, thereby exerting a suppressive effect on cancer progression." (PMID 39459639, 2024). "The direct, insulin-independent effects of metformin originate from liver kinase B1-mediated activation of AMPK and a reduction in mammalian target of rapamycin (mTOR) signaling and protein synthesis in cancer cells." (PMID 38711049, 2024). "A recent study has suggested the synergistic effects of the combination of immunotherapy drugs and mTOR inhibitors in cancer treatment." (PMID 38791040, 2024).